WNT5A (Wnt family member 5A)
Diseases named in the same sentence as WNT5A in open-access papers (continued):
Sharing a sentence is not in itself a finding about the gene and the disease.
breast carcinoma (continued). "Wnt5a stimulation induces the ROR1-dependent activation and nuclear accumulation of the TAZ protein, thereby enhancing the stemness of breast cancer cells, resulting in improved cell survival, migration and drug resistance." (PMID 31382410, 2019). "The only references in such regard is that activation of NF-κB by Wnt5a was shown to be required for BMP-6 mRNA and MMP7 upregulation in LNCaP and breast cancer cells, respectively." (PMID 31510045, 2019). "The authors further established that WNT5A signaling also inhibits monocarboxylate transporter 1 (MCT1) expression, thereby inhibiting lactate uptake in breast cancer cells." (PMID 30171384, 2018). "Later, in an independent study, it was shown that WNT5A signaling impairs CD44-AKT signaling, leading to impaired breast cancer cell migration and invasion." (PMID 30171384, 2018). "The investigators delineated a specific WNT5A signaling axis, i.e., FZD3/Gαs/cAMP/PKA, to be responsible for the DARPP-32 and CREB-dependent anti-migratory effects in breast cancer cells." (PMID 30171384, 2018). "In support of our present finding that WNT5A impairs the expression of MCT1, inhibition of MCT1 has been shown to impair lactate transport as well as migration and invasion of breast cancer cells." (PMID 29069720, 2017). "Specifically, it has been shown that the WNT5A-mediated suppression of CD44 reduces the downstream AKT signaling, which further explains how WNT5A signaling impairs breast cancer cell migration and invasion." (PMID 28886116, 2017). "In these studies we sought to evaluate the effect of the same TLR signaling inhibitor, C10, on human MCF-7 breast cancer cells that exhibit high constitutive levels of TLR3 and Wnt5a RNA." (PMID 29371911, 2017). "To investigate if the WNT5A-mediated inhibition of β-catenin is mediated through altered ERK1/2 signaling, we next treated the breast cancer cell lines with U0126, a highly selective inhibitor of both MEK1 and MEK2 resulting in impaired ERK signaling." (PMID 29069720, 2017). "Our initial findings revealed that WNT5A signaling impairs lactate production in breast cancer cells and that PFKP expression relates to prognosis of breast cancer patients." (PMID 29069720, 2017). "In basal-like breast cancer, the TWIST protein, a well known EMT inducer, is specifically diacetylated by KAT5 to interact with BRD4 and activate WNT5A." (PMID 27581651, 2016). "RAB35 is well characterized in the Wnt5a pathway, which was identified as a potent modulator of MCF-7 breast cancer cell migration." (PMID 27430308, 2016). "In our previous studies, we also demonstrated that the role of WNT5A in increased adhesion is mediated by its ability to phosphorylate DDR1, resulting in the reduced migration of breast cancer cells." (PMID 27623766, 2016). "Using an ERK1/2 inhibitor to mimic the inhibition of ERK1/2 activity by WNT5A, we confirmed a link between ERK1/2-MAPK signaling and CD44 expression in breast cancer cells." (PMID 27623766, 2016). "To address this possibility, we employed a mouse model of breast cancer with tumors driven by the MMTV-PyMT oncogene in wild-type and Wnt5a-null background." (PMID 27500936, 2016). "The present study demonstrated that WNT5A signaling can suppress CD44 protein expression and signaling, which supports the use of a WNT5A agonist in the treatment of breast cancer patients." (PMID 27623766, 2016). "miRNA-374a promotes EMT and metastasis in breast cancer cells both in vivo and in vitro via targeted downregulation of negative regulators of WNT/β-catenin signaling such as WNT-5A." (PMID 26514730, 2016). "WNT-5A induces RhoA activation via DVL and Daam1 in breast cancer cells or via PI3K/AKT signaling in gastric cancer cells." (PMID 26514730, 2016). "To investigate the role of altered ERK1/2 signaling in the WNT5A-mediated inhibition of CD44, we treated breast cancer cell lines with U0126 (a selective inhibitor of MAP kinase)." (PMID 27623766, 2016).
breast carcinoma (continued). "The experimental data presented herein corroborate the relationship between the expression levels of WNT5A and CD44 in clinical breast cancer samples and their relation to disease-free survival and cumulative survival of patients with breast cancer." (PMID 27623766, 2016). "The relative reduction in nucleolar area mediated by Wnt5a was even more pronounced in the triple negative human breast cancer cell line (TNBC), BT549, indicating that these effects of Wnt5a are found in other breast cancer cell lines." (PMID 27500936, 2016). "In coculture systems, breast cancer cells and basal cell carcinoma (BCC) cells provoked macrophages to produce Wnt5a." (PMID 27608847, 2016). "We clearly showed that WNT5A suppresses CD44, which consequently reduces downstream AKT signaling in breast cancer cells." (PMID 27623766, 2016). "Here, we report that PRA mediates the P4-induction and UPA-inhibition of the expression of both WNT5A and LGR4, suggesting an essential function of PRA-mediated, P4 triggered- breast cancer cell proliferation." (PMID 26474308, 2015). "Towards this goal, expression of Wnt5A and ABCB1 in biopsies from 24 pre-and post-chemotherapeutic-treated breast cancer patients were analyzed." (PMID 25401518, 2014). "miRNA-374a promotes breast cancer metastasis by downregulating WIF1, PTEN and WNT5A expression, consequently activating WNT/β-catenin signaling." (PMID 25491321, 2014). "Recently, a WNT5A peptide agonist, FOXY-5 was shown to inhibit breast cancer metastasis in an in vivo mouse model." (PMID 23484019, 2013). "Consequently, the previous and the present findings are particularly interesting since they suggest that Wnt-5a, a single biomarker determined by immunohistochemistry, could be a useful marker in the clinical setting for both pre- and postmenopausal breast cancer patients." (PMID 23990917, 2013). "Together, these data point to the ability of WNT‐5A signaling to restrict the activity of ERK1/2 via a Cdc42‐dependent mechanism that results in impaired migration and invasion of breast cancer cells." (PMID 23727359, 2013). "In the present study, WNT‐5A activated Cdc42 in MDA‐MB468 and MDA‐MB231 breast cancer cell lines (both ATCC‐certified and ‐characterized)." (PMID 23727359, 2013). "Translational regulation of WNT‐5A mRNA indicates that the WNT‐5A mRNA level in human breast cancer tissue differs from the WNT‐5A protein level in the same tissue sample." (PMID 23727359, 2013). "To assess the effect of Wnt5a on breast cancer cell migration, we treated MDA-MB-231 cells with different doses of recombinant Wnt5a (rWnt5a), and measured the migration rate by wound healing assay." (PMID 22655072, 2012). "We found neither ROR1 nor WNT5a upregulation in ER+ models after Dex treatment, highlighting that the output of GR signaling is context and breast cancer subtype-dependent." (PMID 41261233, 2026). "Furthermore, recent research has demonstrated that CXCR4 is critical for maintaining breast cancer stemness and plays a role in resistance to CDK4/6 inhibitors through the activation of the WNT5A/β-catenin signaling pathway." (PMID 40362664, 2025). "Upon co-culture with TAMs, the invasiveness of the breast cancer cell line MCF-7 in a Boyden chamber assay was drastically increased, an effect which could be emulated by addition of recombinant WNT5A." (PMID 36982422, 2023). "Some previous reports have shown a negative correlation with WNT5A signaling and breast cancer cell migration through the addition of recombinant WNT5A(rWNT5A) to MDA-MB-231 cells." (PMID 36107918, 2022). "The relapse-free survival rate in patients with Wnt5a-positive breast cancer was significantly lower than that in patients with Wnt5a-negative breast cancer (P = 0.047)." (PMID 34047951, 2021). "The recurrence rate of Wnt5a-positive breast cancer patients is significantly higher than that of Wnt5a-negative breast cancer patients." (PMID 34047951, 2021).
breast carcinoma (continued). "Of note, the 5-year relapse-free survival (RFS) rate is significantly lower in Wnt5a-positive versus -negative breast cancer." (PMID 34047951, 2021). "A study has shown that GPC6 promotes the invasive migratory capacity of breast cancer cells through non-canonical Wnt5a signaling, where NFAT signaling promotes GPC6 expression in the cells." (PMID 33742285, 2021). "The 8-year RFS rate of Wnt5a-positive breast cancer patients was lower than that of Wnt5a-negative patients [(91.9% (95% CI = 85.1–98.7) vs 98.6%, (95% CI = 96.0–100.0), P = 0.047]." (PMID 34047951, 2021). "Previously, we reported that Wnt5a-positive breast cancer can be classified as estrogen receptor (ER)-positive breast cancer; its prognosis is worse than that of Wnt5a-negative breast cancer." (PMID 34047951, 2021). "Together, our study supports the notion that stromal CAFs promote VEGF-independent pro-angiogenesis processes in breast cancer, and FOSL2-mediated Wnt5a expression and activation of downstream signaling are crucial for VEGF-independent angiogenesis of breast CAFs." (PMID 33754039, 2021). "The early dissemination and metastasis of Her-2+ breast cancer are also driven by the noncanonical Wnt (Wnt5a, Wnt5b, and Wnt11)-dependent EMT-like pathway." (PMID 33234169, 2020). "Wnt5a also induced ROR1-dependent tyrosine phosphorylation of cortactin (Y421), which recruited ARHGEF1 to activate RhoA and promote breast-cancer-cell migration; such effects could be inhibited by cirmtuzumab, a humanized mAb specific for ROR1." (PMID 31667337, 2019). "Non-canonical Wnt receptor Fzd2 and its ligands Wnt5a/b are elevated in metastatic breast cancer cell lines and in high-grade tumors and that their expression correlates with markers of EMT." (PMID 31462314, 2019). "Moreover, Twist1 has been shown to bind directly to the ROR1 promoter and induce ROR1 expression in basal-like breast cancer, as well as to regulate the transcription of ROR1 ligand Wnt5a." (PMID 31382410, 2019). "Interestingly, CDC42 was identified from this analysis; cdc42 plays a role in filopodia formation and breast cancer cells expressing DARPP-32 have, in a study looking at Wnt-5A activation of DARPP-32, been shown to have lower cdc-42 activity." (PMID 31740718, 2019). "In this regard, we found that cirmtuzumab could block the capacity of Wnt5a to induce ROR1 to complex and phosphorylate cortactin, recruit ARHGEF1, and activate RhoA, thereby suppressing breast-cancer-cell migration/metastasis." (PMID 31667337, 2019). "The majority of the previous reports on Wnt5a-positive breast cancer classified these cancers based solely on the presence or absence of Wnt5a expression, without regard to subtype." (PMID 29765514, 2018). "While a significant correlation between the immunohistochemical disappearance of Wnt5a expression and poor prognosis has been reported, these studies do not distinguish between breast cancers subtypes." (PMID 29765514, 2018). "Detailed investigation of WNT5A signaling revealed downregulation of the β-catenin-phosphofructokinase-platelet type (PFKP) axis, thereby directly affecting lactate production and migration of breast cancer cells." (PMID 30171384, 2018). "However, the authors demonstrated that WNT5A-triggered Cdc42 activation inhibits ERK1/2-MMP-9 signaling, resulting in impaired breast cancer migration and invasion." (PMID 30171384, 2018). "We identified two peptide sequences that had the ability, similar to rWNT5A, to impair migration of breast cancer cells lacking endogenous expression of the WNT5A protein." (PMID 30171384, 2018).
breast carcinoma (continued). "In 153 cases of ER-positive breast cancer, ALCAM was expressed in 69% of Wnt5a-positive breast cancers but only 27% of Wnt5a-negative breast cancers, a statistically significant correlation between Wnt5a and ALCAM expression (κ = 0.444; P < 0.001)." (PMID 29765514, 2018). "In subsequent animal experiments with WNT5A-negative 4T1 breast cancer cells inoculated orthotopically in mammary fat pads, we were able to show that treatment every 4th day with Foxy5 for up to 24 days significantly reduced the metastatic spread by 70–80%." (PMID 30171384, 2018). "The idea would then be to reconstitute WNT5A signaling in patients who have been diagnosed with breast cancer with low or absent endogenous expression of WNT5A protein in their cancer tissue." (PMID 30171384, 2018). "We examined the expression of Wnt5a and ALCAM in breast cancer specimens." (PMID 29765514, 2018). "The recurrence-free survival was shorter in breast cancer patients with Wnt5a expression than in those without (P = 0.024)." (PMID 29765514, 2018). "We found that human MCF-7 breast cancer cells express high basal levels of TLR3 and Wnt5a RNA." (PMID 29371911, 2017). "RhoA is involved in Wnt5a signaling and promotes the migration of MDA-MB-231 breast cancer cells." (PMID 28289332, 2017). "The use of Foxy-5 to reconstitute WNT5A functions has already been proven effective in reducing spontaneous metastases to the lungs and liver without affecting primary tumor growth in a breast cancer mouse model." (PMID 28886116, 2017). "For instance, Wnt5a and Wnt5b were found to be overexpressed in basal-like MDA-MB-231 cells compared to less aggressive LumA MCF-7 cells and their expression levels were also elevated together with Ror1/Ror2 in breast cancer brain metastases." (PMID 28695110, 2017). "Because we have shown that WNT5A inhibits PFKP expression in breast cancer cells and that PFKP directly regulates aerobic glycolysis, migration and invasion of breast cancer cells, we investigated the mechanism of WNT5A-mediated regulation of PFKP expression in breast cancer cells." (PMID 29069720, 2017). "WNT5A protein expression was not detectable in either breast cancer cell line (MDA-MB468 and MDA-MB231) compared to HB2 cells, which endogenously express WNT5A protein." (PMID 27623766, 2016). "Moreover, treatment with either a WNT5A agonist or a monoclonal antibody against CD44 in mouse breast cancer models impaired tumor progression, which suggests a therapeutic possibility." (PMID 27623766, 2016). "Our experiments showed that WNT5A inhibited CD44 expression in breast cancer cells but not in HB2 cells." (PMID 27623766, 2016). "EMT reversal is clearly not responsible for the WNT5A-mediated inhibition of breast cancer cell migration and invasion; therefore, we sought alternative explanations for this phenomenon." (PMID 27623766, 2016). "In breast cancer, non-canonical Wnt signaling by Wnt5a has been reported to antagonize tumor growth." (PMID 27500936, 2016). "Evidence that DVL1 can be specifically localized to the nucleolus was further shown by ectopic expression of FLAG-tagged DVL1 in fibroblasts lacking endogenous DVL1 protein as well as by immuno-electron microscopy of MCF7 cells stably expressing Wnt5a, and of MDA-MB-231 breast cancer cells." (PMID 27500936, 2016). "Contrary to our expectations, we did not observe any changes in the EMT status of breast cancer cells, either after treatment with rWNT5A or stable transfection with a WNT5A plasmid, despite the parallel WNT5A-induced inhibition of migration and invasion." (PMID 27623766, 2016). "Besides, Wnt5A expression level was positively correlated with ABCB1 and VEGF expression levels in the clinical breast cancer tissues." (PMID 25401518, 2014).
breast carcinoma (continued). "Taken together, the Wnt5A signaling pathway was shown to contribute to regulating the drug-resistance protein ABCB1 and β-catenin-related genes in antagonizing the toxic effects of doxorubicin in the MDR cell lines and in clinical breast cancer samples." (PMID 25401518, 2014). "Microarray analysis of PIAS1 knockdown breast cancer cells has uncovered an essential role of PIAS1 in the suppression of a group of genes previously known to be clinically relevant to breast cancer, such as WNT5A." (PMID 24586797, 2014). "In a screen of Wnt mRNA expression levels in various established human breast cancer cell lines, down-regulation of non-canonical Wnts, including Wnt5a, and increased expression of canonical signaling Wnts was correlated with a more aggressive phenotype." (PMID 25401739, 2014). "The highly invasive breast cancer cell lines, MDA-MB-231 and 4T1, express very low levels of WNT5A." (PMID 23484019, 2013). "This approach enabled us to compare the possible difference in Wnt-5a-induced effect on cell invasion in ER expressing cells with those lacking ER expression in breast cancer cells with an identical phenotype." (PMID 23990917, 2013). "This resulted in a design of both in vitro and in vivo experiments where reconstitution of Wnt-5a signaling was only tested in breast cancer cells lacking endogenous expression of both Wnt-5a and ER." (PMID 23990917, 2013). "However, there are some reports that question the ability of WNT‐5A to inhibit the migration of breast cancer cells and suggest that WNT‐5A increases migration of breast cancer cells." (PMID 23727359, 2013). "Significant expression of WNT5A was observed in all of the patients’ breast cancer tissues and in the MB-435 and MB-231 cells, but not in the MCF-7 and T47D cells." (PMID 24683528, 2013). "We also observed a lack of expression of a subset of genes including WNT5A mRNA in ER+ve breast cancer cell lines." (PMID 23861811, 2013). "Post-translational protein targets of WNT5A in breast cancers have also been identified however, a global comparison of gene expression in WNT5A low and high expressing breast cancer cells has not been reported." (PMID 23484019, 2013). "The non-transforming Wnt5a can inhibit breast epithelial cell migration and predicts longer disease-free survival for patients with breast cancer." (PMID 22655072, 2012). "We found that, similar to the findings by other investigators, Wnt5a expression pattern in normal breast cells MCF-10A was similar to that in breast cancer cells (data not shown)." (PMID 22655072, 2012). "Stimulation of breast cancer cells with Wnt5a-conditioned media does not significantly impact β-catenin phosphorylation, whereas stimulation with media conditioned with the potent canonical Wnt activating ligand Wnt3a significantly reduces β-catenin phosphorylation." (PMID 37147680, 2023). "Thus, Wnt5a-dependent migration and Dvl2 phosphorylation in breast cancer cells is driven by engagement of a non-canonical Wnt signaling pathway rather than canonical Wnt signaling." (PMID 37147680, 2023). "In addition to the expression correlation between ATBF1 and WNT5A, we further investigated whether ATBF1 regulated the proliferation of breast cancer cells via WNT5A." (PMID 36476423, 2022). "Most importantly, 5 genes were found to be associated with all of the most highly enriched GO terms and KEGG pathways: WNT5A, WNT6, WNT11, WNT5B and LAMA1, which suggested that WNTs may be essential targets of ATBF1 and may contribute to breast cancer tumorigenesis." (PMID 36476423, 2022). "We also examined the expression of these genes in a separate cohort of 698 luminal (ER/PR+) breast cancers using the TCGA dataset, where PIK3CA-mutant cancers displayed significantly higher expression of eight Wnt genes (LEF1, TCF7L1, TCF7L2, CTNNB1, LRP6, SFRP2, WNT5A, and MSX2)." (PMID 34035258, 2021). "Therefore, the roles of WNT5A and WNT5B in breast cancer need further research." (PMID 34017835, 2021).